ENSG00000283208 (novel protein)
Gene: Protein-coding gene on chromosome 13 (76,992,078 to 77,129,589, forward strand). Ensembl gene ENSG00000283208.
Genetic constraint (gnomAD): Loss-of-function variants: 21 observed, 19.95 expected, observed/expected ratio (o/e) 1.05, 90% interval 0.75 to 1.51. Missense variants: 240 observed, 241.39 expected, observed/expected ratio (o/e) 0.99, 90% interval 0.89 to 1.11. Synonymous variants: 91 observed, 87.83 expected, observed/expected ratio (o/e) 1.04, 90% interval 0.87 to 1.23.